CD80 (CD80 molecule)
Diseases named in the same sentence as CD80 in open-access papers (continued):
Sharing a sentence is not in itself a finding about the gene and the disease.
colon carcinoma (29 papers, 2007 to 2025). "Among cancers, previous studies have reported that low surface expression of CD80 was associated with the immune escape mechanism of colon cancer, and upregulating CD80 on tumor cell surface successfully enhances antitumor immune responses." (PMID 35814211, 2022). "In colon cancer, low CD80 expression is associated with immune escape and plays an important role in the immune surveillance of the lesion." (PMID 34852825, 2021). "Similar to this antiviral effect, our results suggest that a decrease in CD80/CD86 expression may be associated with CD8+ T cell reduction in the tumor microenvironment of colon tumor growth of S100a4-Cre; Ext1f/f mice." (PMID 36809261, 2023). "Furthermore, our in vitro experiments showed that the MMR deficient cell line HTC-15 had a significantly higher CD80 expression than the MMR proficient colon cancer cell line HT-29." (PMID 26496037, 2015). "Intriguingly, moderate cell surface expression of CD80 has been reported as an immune evasion strategy in certain cancers, such as colon carcinoma and even tumor-initiating stem cells." (PMID 40746567, 2025). "CD80 is recognized as an important co-stimulatory molecule responsible for eradication of tumor cells; in colon cancer, CD80 coordinates the immune surveillance for precancerous lesions." (PMID 34120619, 2021). "We found that lipotecan significantly upregulated the levels of the antigen presentation markers MHC class I and CD80 in human and mouse colon cancer cell lines." (PMID 33799527, 2021). "Seven checkpoint-related genes (BTLA,CD80, CD86, CTLA4, IDO1, PDCD1LG2, and TIGIT) had decreased expression in the KRAS-mutated group, providing potential opportunities for immunotherapy in colon cancer." (PMID 33254149, 2020). "In a colon cancer cell line, oxidative stress and reactive oxygen species were able to increase the expression of CD80, however elevated CD80 levels were mainly found in preneoplastic colon mucosa biopsies." (PMID 32957644, 2020). "Some checkpoint-related genes (BTLA, CD80, CD86, CTLA4, IDO1, PDCD1LG2, and TIGIT) had decreased expression in the KRAS-mutated group, providing potential opportunities for immunotherapy in colon cancer." (PMID 33254149, 2020). "Our data demonstrated that in colon cancer cells CD80 induction by oxidative stress was mediated by two different MAPK pathways converging to the transcription factor STAT3." (PMID 31072360, 2019). "Altogether, these data suggest that ROS induce CD80 expression via MAPK pathways that activate STAT3 in colon cancer epithelial cells." (PMID 31072360, 2019). "In vitro, CD80 upregulation was induced by oxidative stress in colon cancer cells and primary colon epithelial cells." (PMID 31072360, 2019). "Heterogeneity of TAM phenotype was described in different tumour types and at different locations of the same tumour e.g. in colon cancer patients, CD80+, CD86+ and HLA-DR+, as well as CD163+, CD86+, CCR2+ cells were described." (PMID 26838097, 2016). "In vitro inhibition of DNA methyltransferases significantly enhances CD80 expression in colon cancer cells." (PMID 27377375, 2016). "We compared the amounts of integrins αvβ3 and αvβ5 and also of CD80 expressed on the cell surfaces of the colon carcinoma cell lines with those on A549 cells." (PMID 21455297, 2011). "Moreover, transfection of CD80 plasmids into colon carcinoma cells enhanced immunogenicity and led to tumor rejection, whereas silencing CD80 abrogated tumorigenicity." (PMID 40746567, 2025). "In fact, we have demonstrated that simultaneous secretion of an anti-CEA x anti-CD3 diabody and a tumor-specific co-stimulatory ligand comprising the extracellular portion of CD80 fused to an anti-CEA antibody increased anti-tumor activity in human colon carcinoma xenografts." (PMID 32903593, 2020).
colon carcinoma (continued). "Furthermore, we showed that the interaction between CD80+ human colonic epithelial cells and activated CD8+ T cells is required for an effective immune surveillance process in ulcerative colitis associated colon cancer." (PMID 31072360, 2019). "Since low surface expression of CD80 is an immunoescape mechanism of colon carcinoma, we speculate that the tumor suppressor role of STAT3 in the later stages of colon cancer progression may be explained by its ability to enhance CD80 expression." (PMID 31072360, 2019). "It was difficult to assess whether CD80 also acts as a receptor for Ad11 on colon carcinoma cells, as its expression was undetectable." (PMID 21455297, 2011). "This study provide evidence for a major role of CD80 in orchestrating immune surveillance of colon preneoplastic lesions and might help to develop novel approaches that exploit anti-tumor immunity to prevent and control colon cancer." (PMID 31072360, 2019). "The results showed that PDCD1LG2, ICOS, CD86, CD80, CD48, and CD274 showed a significant exclusion situation from RFX1 expression in colon cancer." (PMID 41425715, 2025). "The expression levels of CD80, CD86, and MHC-I on CD11c+MHC-II+ splenic DCs from mice inoculated with murine colon carcinoma cells were lower when compared with normal mice." (PMID 33105813, 2020). "Furthermore, in vitro experiments revealed that CD80 expression was higher in the HTC-15 cell line, which has a MSI-H status, than in the HT-29 MSS colon cancer cell line." (PMID 27880934, 2016). "In addition, reactive oxygen species could induce CD80 expression via the JNK and p38 MAPK pathways, that activated STAT3 transcription factor in colon cancer epithelial cells." (PMID 31072360, 2019).
lupus (29 papers, 2006 to 2025). "An anti-CD80 mAb has been employed to inhibit immune response and attenuate severity of a murine lupus model." (PMID 40211396, 2025). "Studies have found that the expression of CD80 on the surface of T cells in patients with systemic lupus erythematosus is increased, and CD80 is mainly expressed on CD4+ T cells." (PMID 39575257, 2024). "We perceived a remarkable increase of mDCs expressing CD80 in patients suffering from lupus compared to control subjects (p = 0.002)." (PMID 31507612, 2019). "Lupus antigen presenting cells have functional impairments such as an inability to induce the immuneregulatory ligands PD-L1 and CD80." (PMID 28944101, 2017). "Blockade of CD80 by monoclonal antibody has been shown in the pristane-induced lupus mouse model to attenuate both the inflammatory response and the severity of SLE hallmarks." (PMID 24945254, 2014). "In a pristane-induced lupus-like disease mouse model, monoclonal antibody against CD80 was shown to be able to attenuate inflammatory response and severity of lupus-like signs." (PMID 24000287, 2013). "We found that DCs from lupus-prone mice expressed levels of CD80 and CD86 comparable to those ofBALB/c and B6 DCs, in terms of both percentage of positive cells and MFI (not shown)." (PMID 16507174, 2006). "We show here that DCs from diseased NZM2410 lupus-prone mice have an altered costimulation pattern, with an abnormal ratio of CD80 to CD86 due to decreased levels of CD80 and normal levels of CD86." (PMID 16507174, 2006). "We found that in lupus-prone mice, after the onset of the disease, DCs expressed an abnormal state of activation with decreased levels of CD80 and CD54, normal levels of CD86, and a specific increase in cells expressing CD40." (PMID 16507174, 2006). "Our previous study showed that CD14+CD16+ monocytes in patients with systemic lupus erythematosus showed inflammatory phenotype, with increased CD80, CD86, HLA-DR, and CX3CR1, which could promote Th17 response." (PMID 32958023, 2020). "In addition, we found the UC-MSCs induced CD1c+DCs in the lupus patients exerted tolerogenic properties by decreasing expression of CD80, CD83, CD86 and HLA-DR, decreasing production of TNFα and keeping production of IL-10." (PMID 31175312, 2019). "Because these data were collected from a large number of mice, especially in the adult populations, and in separate experiments over a period of months, such consistency strengthens the significance of the altered expression ratio of CD80 to CD86 observed in adult mice with lupus." (PMID 16507174, 2006). "In our studies, we found that elevation of the expression level of miR-1246 in lupus B cells could decrease the expression of EBF1 causing the downregulation of CD40, CD80, and CD86 which are co-stimulatory molecules required for full B cell activation and IgG secretion." (PMID 25789080, 2015). "The aim of this study was to investigate the distribution and phenotypical characteristics of IL-17 producing T-cells in SLE, in particular in patients with lupus nephritis, with emphasis on the expression of CD80 and CD134." (PMID 20653937, 2010). "This locus has also been reported as a susceptibility region for celiac disease, multiple sclerosis, systemic lupus erythematosus, and vitiligo, represented by rs11712165 in ARHGAP31, rs2293370 in TIMMDC1, and rs6804441 and rs148136154 in CD80, respectively." (PMID 30643196, 2019). "KEGG analysis revealed the systemic lupus erythematosus pathway involving CD86, TNF, C4, FCGR2B, CD80, C3, CD40, and C1S." (PMID 28976997, 2017). "Since pDCs are essential for lupus like disease development in mice, we next examined the expression of CD40 and CD80 on the surface of pDCs following stimulation with TLR9 agonist (CpG)." (PMID 27232337, 2016). "In agreement with previous studies, the expression of CD80, CD86, and CD40 after culture with LPS was diminished in moDC from lupus patients compared with healthy controls." (PMID 27057555, 2016).
lupus (continued). "Lupus DCs showed an altered ex vivo costimulatory profile, with a significant increase in the expression of CD40, decreased expression of CD80 and CD54, and normal expression of CD86." (PMID 16507174, 2006). "Whereas the alteration in CD80/CD86 ratio is evident only after the onset of the disease, the overexpression of CD40 precedes the onset of lupus and is sustained even during the course of the disease." (PMID 16507174, 2006). "DCs from young lupus-prone NZM2410 mice, before the development of the disease, expressed normal levels of CD80 and CD86 but already overexpressed CD40." (PMID 16507174, 2006). "In this study, we evaluated the gene polymorphisms of the ligand genes corresponding co-stimulatory system that were expressed on antigen-presenting cells (CD80, CD86, ICOSLG, and PDL1) from 60 systemic lupus erythematosus (SLE) patients and 60 healthy controls." (PMID 38361527, 2023). "Moreover, we also noted that the activation markers (MHC II, CD80, and CD86) on dendritic cells were significantly elevated in spontaneous lupus NZM2328 mice that were fed the HSD diet compared with those that were fed the NSD diet." (PMID 32296043, 2020). "Our study herein found that pDC activation markers, including MHC-II molecules, CD80, IFNα and IFN signature, were upregulated in lupus-prone mice at the advanced lupus stage, thereby indicating that pDCs were activated and released IFNα in lupus-prone mice." (PMID 26879679, 2016). "cDC in the blood of SLE patients or secondary immune tissues of lupus-prone mice have been shown to exhibit elevated expression of CD40, CD80, CD86, PD-L1, and PD-L2, suggesting that cDC in lupus may be activated and immunogenic." (PMID 27034965, 2016). "The upregulation of CD86 but not CD80 on APCs is observed in other diseases as well such as systemic lupus erythematosus." (PMID 27348308, 2016). "We expanded our analysis to the co-stimulatory marker CD80, which had been shown to be a potent regulator of IgG secretion by previously activated B cells, and CD95, which had been correlated with disease activity in systemic lupus erythematosus (SLE)." (PMID 22770118, 2012). "Moreover, the comparable levels of CD80 and CD86 in BALB/c and B6 DCs confirmed the feasibility of using these two strains of mice for comparison with the lupus-prone strain." (PMID 16507174, 2006). "However, the maturation and activation markers on dendritic cells, including MHC II, CD80, and CD86, were significantly increased in cells that were isolated from sodium chloride-pretreated BMDC-ALD-DNA-induced lupus mice compared to those of control lupus mice." (PMID 32296043, 2020). "The abnormal functions of APCs in SLE may be related to downregulation of their cell surface PD-L1 expression, leading to failed antagonization of CD80/CD86-mediated T-cell-signaling transduction and overactivation of effector T cells, thereby contributing to lupus onset." (PMID 23533458, 2013). "To validate our unexpected finding that B cells were not activated in lupus patients we purified B cells from the same three patients and quantified levels of CD80, a molecule found on the surface of activated B cells that provides a costimulatory signal for T cell activation." (PMID 19568420, 2009). "Despite previous reports in the literature indicating increased autoantibody production in the relatives of lupus patients, the proportions of activated B cells, as determined by expression levels of CD69, CD80, and CD86, were not increased in the family members of our lupus patients." (PMID 18783591, 2008).
ovarian carcinoma (25 papers, 2011 to 2024). A malignant neoplasm originating from the surface ovarian epithelium. "In the myeloid compartment, CD80, a known immunosuppressive marker, was expressed and this protein is associated with tumor progression and immune tolerance in ovarian cancer." (PMID 36077756, 2022). "Relative to monoculture, a majority of the PBMC-derived macrophages displayed CD80 marker upon co-culture with ovarian cancer cells." (PMID 39287565, 2024). "MiR-424 has been reported to be inversely correlated with PD-L1 and CD80 expressions in ovarian cancer." (PMID 38439112, 2024). "Statistically significant higher median serum levels of CD27 and CD80 proteins were found in highly advanced ovarian cancer (stage III–IV) compared to low advanced ovarian cancer (stage I–II) (p = 0.02 and p = 0.03, respectively)." (PMID 35204342, 2022). "The median concentrations of the studied proteins (BTLA, CD27, CD28 and CD80) were statistically significantly higher in serum of patients in the ovarian cancer group (group A) compared to serum concentrations in patients with benign ovarian lesions (group B)." (PMID 35204342, 2022). "The cutoff values for BTLA, CD27, CD70, CD28 and CD80 that were elevated in the serum of patients with ovarian cancer were calculated using ROC curve analysis." (PMID 35204342, 2022). "For example, CD80 expression was studied, and high levels of CD80 expression were observed on Gr-1+ CD11b+ ovarian cancer cells." (PMID 35204342, 2022). "Previous studies have investigated CD80 from different aspects and with different uses, but there are few data presenting CD80 as a molecule used in the diagnosis and prognosis of ovarian cancer, where the test material is patient serum and peritoneal fluid." (PMID 35204342, 2022). "Our results further revealed an association between higher CD80/CD163 ratio at the tumor IF and improved survival, similarly to what was reported in ovarian cancer." (PMID 31481956, 2019). "A chimeric virus of HAdV5 with the human adenovirus serotype 3 fiber knob (Ad5/3) increases gene uptake in dendritic cells, ovarian cancer, and malignant glioma cells via binding to CD80 and CD86." (PMID 25933160, 2015). "It was concluded that CD80-dependent responses to myeloid suppressor cells may contribute to tumor tolerance and the progression of ovarian carcinoma." (PMID 35204342, 2022). "BTLA, CD28 and CD80 may also contribute to the diagnosis of ovarian cancer, but their possible insufficient sensitivity and specificity as diagnostic markers should be taken into account." (PMID 35204342, 2022). "ACOD1-/- MSLN-CAR-iMACs expressed more pro-inflammatory marker proteins (CD80 and CD86) after being co-cultured with HO-8910 ovarian cancer cells for 24 h." (PMID 37723178, 2023). "For instance, in chemoresistant ovarian cancer, miR-424 has been proved to regulate the PD-1/PD-L1 and CTLA-4/CD80 pathways." (PMID 33806327, 2021). "The activation of DCs (CD86 +, CD80+, CD83+, HLA-DR+), CTLs (CD3+CD8+) and NKT (CD3+CD56+) cells were all increased in 6B11-OCIK of the three patients during in vitro culture and showed good killing effect on ovarian cancer cells." (PMID 34408750, 2021). "In mouse ovarian cancer model, MDSC enhanced the expression of CD80 through direct contact with tumour cells, and CD80 could bind to CTLA-4 on Tregs to enhance the immunosuppressive function of Tregs." (PMID 32680511, 2020). "In ovarian cancer cell lines and in ovarian cancer tissues, it was reported that the expression of miR-424 negatively correlated to the expression of CTLA-4/CD80 and PD-L1, and that the restoration of miR-424 re-established T cells activity, reverted chemoresistance and increased free survival time." (PMID 32316552, 2020). "Accordingly, in an ovarian carcinoma-bearing mice model, IFN-γ-stimulated M-MDSC increased MHC class II, CD80, and IL-10 expression, and induced CD4+CD25+ Treg in a CTLA-4/CD80-dependent manner, which is in line with our results on IL-10-producing GM-CSF/IL-6 M-MDSC." (PMID 30936876, 2019).
ovarian carcinoma (continued). "CD80 has been extensively studied for its role in immune responses, yet no focused analysis of SNPs and ovarian cancer outcome has been reported, to our knowledge." (PMID 23382860, 2013). "To test this hypothesis, we analyzed M1 macrophage markers, including CD80, CD32, and CD64, and M2 macrophage markers, including CD68, CD206, and CD163, in HERV-K119 env KO THP-1 cells and compared them with those in HERV-K119 env KO OVCAR3 ovarian cancer cells." (PMID 37958549, 2023).